ABCA4 (ATP binding cassette subfamily A member 4)
Diseases named in the same sentence as ABCA4 in open-access papers (continued):
Sharing a sentence is not in itself a finding about the gene and the disease.
Cone rod dystrophy (continued). "It is well known that ABCA4 mutations are heterogeneous and cause various forms of retinal dystrophies, which include STGD, retinitis pigmentosa, age-related macular degeneration (AMD), and cone-rod dystrophy." (PMID 25922843, 2015). "It is now generally believed that mutations in ABCA4 result in a spectrum of related retinal dystrophies, including STGD, bull’s eye maculopathy, retinitis pigmentosa, cone rod dystrophy and age-related macular degeneration." (PMID 24632595, 2014). "ABCA4 mutations are also associated with all juvenile HMD, recessive RP, and cone-rod degeneration." (PMID 19551904, 2009). "Canine ABCA4 has been studied as a candidate gene for cone-rod degeneration in the pit bull terrier, although no mutations were found." (PMID 18593457, 2008). "In addition to STGD1, mutations in ABCA4 result in a spectrum of related retinal degenerative diseases with variable clinical phenotypes, including retinitis pigmentosa-19, age-related macular degeneration, and cone-rod dystrophy." (PMID 30563929, 2019). "There are six phenotypes associated with mutations in ABCA4 in the OMIM database, one of which is cone-rod dystrophy; 65% of patients with cone-rod dystrophy carry a mutation in this gene which lends weight to the hypothesis that ABCA4 is indeed intolerant to mutation." (PMID 25550428, 2015). "Mutations in the ABCA4 gene have been associated with ar transmitted Stargardt disease (STGD1), ar inherited cone-rod dystrophy (CRD) and ar RP." (PMID 17134500, 2006). "This aligns with a diagnosis of ABCA4-IRD, with early onset and a possible later progression into a cone-rod dystrophy, similar to the findings in his brother MST465-II:2 with a sole ABCA4 genotype." (PMID 40269797, 2025). "Three of the genes, CNGB3, CNGA3 and GNAT2, involved in cone degeneration and seven genes and loci, ABCA4, RDH5, CORD8, CORD9, RPGRIP1, GUCY2D and CRX, reported to be involved in cone-rod dystrophies were studied." (PMID 18593457, 2008). "Although mutations in ABCA4 cause over 95% of STGD, patients harbouring variants in this gene may also display different phenotypes: cone-rod dystrophy 3 (CRD3, MIM #604116), and retinitis pigmentosa 19 (RP19, MIM #601718)." (PMID 31766579, 2019).
retinal disease (68 papers, 2007 to 2026). "This study investigates the clinical manifestations of inherited retinal diseases (IRD) associated with dual-gene variant constellations involving biallelic ABCA4 variants." (PMID 40269797, 2025). "A study on ABCA4-associated retinal disease utilized ROs to investigate the c.4539+1321A>G variant, revealing its potential pathogenicity through mis-splicing in photoreceptor cells, resulting in a truncated protein." (PMID 39422807, 2025). "Hypomorphic variants are intriguing and have only recently been recognised as major contributors to ABCA4-associated retinal disease." (PMID 39971915, 2025). "Another recent database study analyzing the ABCA4 gene variants in about 11,000 patients having inheritable retinal disease identified around 1200 unique variants in the ABCA4 gene that were pathogenic or likely pathogenic." (PMID 40725253, 2025). "Findings from the VLP characterization platform aligned well with and extended the existing literature on ABCA4 variants, demonstrating the efficacy of this method in the functional analysis of genetic mutations associated with retinal diseases." (PMID 39222682, 2024). "ABCA4 is the most frequently mutated gene leading to inherited retinal disease (IRD) with over 2200 pathogenic variants reported to date." (PMID 38892127, 2024). "We searched the electronic patient records of our large inherited retinal disease cohort, quantifying numbers of males and females with the more common (non-ABCA4) inherited macular dystrophies (associated with BEST1, EFEMP1, PROM1, PRPH2, RP1L1, and TIMP3)." (PMID 38700873, 2024). "One of these was ABCA4, which is implicated in the most common autosomal recessive inherited retinal disease." (PMID 38760655, 2024). "Splicing defects from deep-intronic variants significantly contribute to the mutational spectrum in ABCA4-associated inherited retinal diseases, necessitating functional validation for their pathological classification." (PMID 38274366, 2024). "The adapted ACMG/AMP classifications provided in this study, in combination with the earlier established severity assessments for ABCA4 variants, will facilitate the interpretation of diagnostic results for ABCA4-AR, the most common recessive retinal disease." (PMID 40225145, 2023). "The ABCA4 variant p.Asn1868Ile (c.5603A>T) has long been shown to be enriched in those with retinal disease compared to controls, but its pathogenicity is typically dependent on the co-occurrence of another cis-acting variant." (PMID 37342033, 2023). "STGD1 is one of the most frequently inherited retinal diseases (IRDs) caused by biallelic mutations in ABCA4, accounting for 12% of IRD-related blindness." (PMID 36359825, 2022). "Variants in a subset of retinal disease genes cause disease phenotypes overlapping with features of ABCA4 disease." (PMID 35353811, 2022). "The high allelic heterogeneity makes molecular genetic analysis of ABCA4-associated retinal disease challenging." (PMID 33732702, 2021). "It is likely that glycosylation plays an important role in the folding or trafficking of ABCA4,as missense mutations at positions 415, 504, and 1588 are linked to retinal diseases." (PMID 33605212, 2021). "Due to its clinicalheterogeneity, many phenocopies—retinal disease caused by other genesresembling ABCA4-associated retinopathy—exist, includingdominantly inherited conditions." (PMID 32278709, 2020). "Stargardt macular degeneration is an inherited retinal disease caused by mutations in the ATP-binding cassette subfamily A member 4 (ABCA4) gene." (PMID 33187113, 2020). "Most of the disease-associated genes were unique to a single retinal disease, with the exception of Abca4, Nmnat1, Casp3, and Crb1, which were each shared across two diseases." (PMID 31527661, 2019). "Complex alleles in ABCA4 have been known since the discovery of its connection with retinal diseases." (PMID 31766579, 2019).
retinal disease (continued). "Since the knowledge of the genetic causes of inherited retinal diseases (IRDs) in Poland is still scarce, the purpose of this study was to identify pathogenic ABCA4 variants in a subgroup of Polish IRD patients." (PMID 31766579, 2019). "In 57% of all MD/CCRD cases (77% of the 185 solved cases), retinal disease was explained by mutations in ABCA4 (n = 94, 37%), PRPH2 (n = 29, 12%) or BEST1 (n = 19, 8%; including 5 a.r. and 14 a.d. mutations)." (PMID 29555955, 2018). "The high allelic heterogeneity makes molecular genetic testing of ABCA4-associated retinal disease very challenging." (PMID 27491360, 2017). "In contrast, we report a statistically significant association of common variants in the ABCA4 gene with retinal disease, assessed by a score-based variance-component test (PSKAT = 0.0055)." (PMID 25884411, 2015). "In this retrospective chart review study, cross-sectional data on the phenotype and genotype of patients under 18 years of age with ABCA4-associated retinal disease from the clinic for inherited retinal dystrophies at the University of Tuebingen were collected." (PMID 40643605, 2025). "As modifying factors are supposed to have an equal impact on the phenotype as the ABCA4 variants themselves and most patients with ABCA4-associated retinal disease have a unique genotype, the clinical findings are considered to be more predictive for the course of the disease than the genotype." (PMID 40643605, 2025). "Additionally, a study exploring the genetic landscape of retinal diseases in northwestern Pakistan identified prevalent mutations in genes such as ABCA4, BBS2 and CNGA1 as the most frequently associated IRD genes." (PMID 40141357, 2025). "Interpretation of ABCA4 variants is crucial for molecular diagnostics in patients affected not only by STGD1 but also other forms of inherited retinal diseases (IRDs), as variants in this gene can be associated with clinical phenotypes that differ substantially from the typical findings in STGD1." (PMID 39766771, 2024). "Biallelic pathogenic variants in ABCA4 are the commonest cause of monogenic retinal disease." (PMID 36178783, 2022). "ABCA4 is the gene most frequently associated with monogenic retinal disease." (PMID 35704304, 2022). "There are over 1000 mutations of ABCA4 known to cause STGD1 and related retinal diseases." (PMID 33546345, 2021). "As in ABCA4-related retinal disease, if an association between ABCA4 variants and HCQ47 were to exist, it may be explained by levels of bisretinoid lipofuscin." (PMID 32976563, 2020). "The complete genetic characterization of the patients will improve the accuracy of diagnosis and their counselling and also will assist in more effective patient selection of genetically confirmed participants for current and future clinical trials for ABCA4-associated retinal diseases." (PMID 29854428, 2018). "Aim of this study is to analyse the clinical picture of a pediatric ABCA4-related retinal disease cohort to evaluate possible inclusion criteria and outcome measures in children for future interventions." (PMID 40643605, 2025). "Having accurate models of STGD1, stratified in mutation and disease severity, is crucial for the holistic understanding of STGD1 and other ABCA4‐mediated retinal diseases." (PMID 36177499, 2023). "Here, we complemented the ABCA4 Leiden Open Variation Database (LOVD) with data from ~11,000 probands with ABCA4-associated inherited retinal diseases from literature up to the end of 2020." (PMID 40225145, 2023). "ABCA4 has been extensively studied in retinal diseases, with few studies on tumors warranting further research." (PMID 36686667, 2022). "We propose that the analysis of functionally-relevant non-coding regions in rhodopsin, ABCA4 and other known retinopathy genes, as identified in this study, would greatly augment our understanding of Mendelian retinal diseases." (PMID 36207300, 2022).
retinal disease (continued). "Variants in ABCA4, PRPH2, and BEST1 alone explained retinal disease in 60.7% of the MD cohort, similar to previously published results (57%)." (PMID 33546218, 2021). "ABCA4 locus resequencing was followed by the analysis of other inherited retinal disease genes by whole exome sequencing (WES)." (PMID 31721179, 2020). "Mutations in ABCA4, PRPH2 and BEST1 were predominant, explaining the retinal disease in 57% of the entire cohort and 74% of the solved cases." (PMID 29555955, 2018). "Transduction efficiency appeared lower in the Abca4−/− mouse compared to wild type with all vectors tested, suggesting an effect of specific retinal diseases on the efficiency of gene delivery." (PMID 23593201, 2013). "In this study, RPGRIP1, RANBP2, NPM1, PDE6D, NPHP5, and ABCA4 genes were selected on the basis of interaction with RPGR or RPGRIP1 or their implication in related retinal diseases, and were investigated as candidate genetic modifiers of XLPRA1." (PMID 17653054, 2007). "Our results imply that rebalancing the local complement activity in inherited retinal diseases may help to prolong neuron survival and avoid potential secondary cell loss, as seen in the GCL of the ABCA4−/− mice." (PMID 33187113, 2020). "MEP-082 was a 46-year-old Caucasian male who was diagnosed with ABCA4-related retinopathy and had no family history of retinal disease." (PMID 36833373, 2023). "The high prevalence of ABCA4-RD combined with its protean phenotypic manifestations that mimic other IRDs and non-monogenic retinal diseases make it a frequently misdiagnosed condition in clinical practice." (PMID 38066771, 2023). "Since no second candidate variant was identified in ABCA4 or ALMS1, both of which have been associated with recessive forms of retinal diseases, these variants alone could not explain the phenotype in the index patient." (PMID 39766771, 2024). "All other participants with this genotype had no record of retinal disease that could be ABCA4 retinopathy." (PMID 37342033, 2023). "The conception of ‘inferred BCVA’, ‘inferred visual impairment’, and ‘inferred ERG’ as quasi-functional outcome measures are not restricted to ABCA4-related retinopathy but might be further applied to other retinal diseases." (PMID 32751377, 2020).
Retinal dystrophy (67 papers, 2006 to 2026). Retinal dystrophy is an abnormality of the retina associated with a hereditary process. "The clinical presentation of MST465-II:1 exhibits hallmark features typical of ABCA4-associated retinal dystrophies, such as progressive atrophy of the outer retinal layers primarily affecting the central macula and flavimaculatus flecks." (PMID 40269797, 2025). "With a prevalence of 1 in 8,000–10,000 people, ABCA4 is the most frequent disease gene causing inherited retinal dystrophies." (PMID 38274366, 2024). "Biallelic pathogenic variants in the gene encoding the ATP-binding cassette transporter ABCA4 are the leading cause of irreversible vision loss in inherited retinal dystrophies (IRDs)." (PMID 39087934, 2024). "In this work, the largest cohort (211 index cases) of Latin American patients with retinal dystrophies due to ABCA4 pathogenic variants is reported." (PMID 39162841, 2024). "Comparison between ABCA4-associated disease and other forms of retinal dystrophy revealed that, for the majority of cases, genetic explanations obtained through this study were in agreement with the diagnosis obtained through clinical examination." (PMID 36672932, 2023). "The ATP-binding cassette subfamily 4 (ABCA4), a transporter, is localized within the photoreceptors of the retina, and its genetic variants cause retinal dystrophy." (PMID 36566289, 2022). "A detailed characterization of the retinal phenotype in patients carrying specific mutations in ABCA4 is crucial to understand disease expression and ensure optimal clinical care for patients with inherited retinal dystrophies." (PMID 34008801, 2021). "Most of these probands carried variants previously identified as complex ABCA4 alleles in retinal dystrophy patients." (PMID 33841504, 2021). "In conclusion, our report provides the first analysis in a Taiwanese cohort of ABCA4-associated retinal dystrophies and their genetic spectrum, genotype–phenotype correlation, visual preservation, and prediction of disease progression." (PMID 33261146, 2020). "In this study, we report different phenotypes of ABCA4-associated retinal dystrophies in the Taiwanese population, its clinical progression, and its relationship with genetic characteristics." (PMID 33261146, 2020). "In this study, we recruited patients with ABCA4-associated retinal dystrophies from the Taiwan IRD project (TIP), which included all patients with IRD with a clinical evaluation and genetic diagnosis via capture-based next-generation sequencing (NGS) testing." (PMID 33261146, 2020). "A previous cohort showed that the most prevalent phenotype of ABCA4-associated retinal dystrophies was STGD1, followed by CRD, and RP." (PMID 33261146, 2020). "We aimed to explore the clinical features, genetic spectrum, and genotype–phenotype correlations of ABCA4-associated retinal dystrophies in Taiwan." (PMID 33261146, 2020). "Mutations in the ATP-binding cassette, subfamily A, member 4 (ABCA4) gene are linked to arguably the most common retinal dystrophy: autosomal recessive Stargardt disease (STGD1)." (PMID 28355279, 2017). "These include familial high-density lipoprotein deficiency (caused by defective ABCA1), neonatal surfactant deficiency (ABCA3), several forms of retinal dystrophies (ABCR/ABCA4) and two types of hereditary keratinization disorders (ABCA12)." (PMID 16968533, 2006). "The reason for this may be that the RPE cells contain accumulated material that has been associated with loss of transport function in ABCA4 retinal dystrophies." (PMID 38984108, 2024). "The most encountered gene within our study cohort was ABCA4, with the contribution of frequent variants broadly consistent with findings described by Cornelis et al20 in a large meta-analysis of published ABCA4-associated retinal dystrophy cases." (PMID 38219857, 2024). "ABCA4 is the gene most frequently implicated in monogenic retinal dystrophies." (PMID 36848389, 2023).